ABCC3 (ATP binding cassette subfamily C member 3)
Description:
ATP-dependent transporter of the ATP-binding cassette (ABC) family that binds and hydrolyzes ATP to enable active transport of various substrates including many drugs, toxicants and endogenous compound across cell membranes. Transports glucuronide conjugates such as bilirubin diglucuronide, estradiol-17-beta-o-glucuronide and GSH conjugates such as leukotriene C4 (LTC4). Transports also various bile salts (taurocholate, glycocholate, taurochenodeoxycholate-3-sulfate, taurolithocholate-3-sulfate) (By similarity). Does not contribute substantially to bile salt physiology but provides an alternative route for the export of bile acids and glucuronides from cholestatic hepatocytes (By similarity). May contribute to regulate the transport of organic compounds in testes across the blood-testis-barrier (Probable). Can confer resistance to various anticancer drugs, methotrexate, tenoposide and etoposide, by decreasing accumulation of these drugs in cells.
Synonyms: MOAT-D; CMOAT2; MLP2; MRP3; EST90757; ABC31
Tractability: Small molecule: a structure with a bound ligand is known; it belongs to a druggable protein family. Antibody: UniProt places it where antibodies can reach, with high confidence; its Gene Ontology location is reachable by antibodies, with high confidence; UniProt predicts a signal peptide or a membrane-spanning region; the Human Protein Atlas places it where antibodies can reach. PROTAC: ubiquitination databases record sites on it; its protein half-life has been measured; a small molecule that binds it is known.
Target class: ABCC subfamily; ATP-binding cassette; Transporter; Primary active transporter
Safety:
Unwanted effects reported when the protein is acted on. In parentheses: how it was acted on, where the effect was seen, and who reports it.
hearing loss (source: ClinPGx)
Gene: Protein-coding gene on chromosome 17 (50,634,609 to 50,692,631, forward strand). Ensembl gene ENSG00000108846.
Subcellular location: Basolateral cell membrane; Basal cell membrane
Subcellular location (Human Protein Atlas): Plasma membrane; Basal body
Pathways (Reactome):
Drug ADME: Aspirin ADME; Paracetamol ADME
Cellular responses to stimuli: NFE2L2 regulating MDR associated enzymes
Metabolism: Recycling of bile acids and salts
Transport of small molecules: ABC-family protein mediated transport
Gene Ontology:
Molecular function: ABC-type glutathione S-conjugate transporter activity; ABC-type xenobiotic transporter activity; ATPase-coupled transmembrane transporter activity; glucuronoside transmembrane transporter activity; icosanoid transmembrane transporter activity; xenobiotic transmembrane transporter activity; ABC-type bile acid transporter activity; ABC-type transporter activity; ATP binding; ATP hydrolysis activity; transmembrane transporter activity
Biological process: leukotriene transport; xenobiotic transmembrane transport; xenobiotic transport; bile acid and bile salt transport; transmembrane transport; transport across blood-brain barrier; xenobiotic metabolic process; carboxylic acid transport; glucuronoside transport
Cellular component: basal plasma membrane; basolateral plasma membrane; plasma membrane; membrane
Genetic constraint (gnomAD): Loss-of-function variants: 119 observed, 166.76 expected, observed/expected ratio (o/e) 0.71, 90% interval 0.61 to 0.83. The upper end of that interval is the gene's LOEUF score, 0.83, which puts it in group 3 of 6, group 1 being the genes least tolerant of losing a copy. Missense variants: 1,856 observed, 2,009.5 expected, observed/expected ratio (o/e) 0.92, 90% interval 0.89 to 0.96. Synonymous variants: 725 observed, 826.51 expected, observed/expected ratio (o/e) 0.88, 90% interval 0.82 to 0.93.
Homologues: Orthologues: chimpanzee ABCC3 (98% identical), macaque ABCC3 (90% identical), dog ABCC3 (85% identical), pig ABCC3 (84% identical), rabbit ABCC3 (84% identical), guinea pig ABCC3 (82% identical), mouse Abcc3 (81% identical), rat Abcc3 (78% identical), Drosophila melanogaster MRP (49% identical), Caenorhabditis elegans mrp-7 (43% identical), Drosophila melanogaster Mrp4 (30% identical), Drosophila melanogaster Mrp5 (29% identical), and 9 more. Paralogues in human: ABCC1 (57% identical), ABCC2 (47% identical), ABCC6 (43% identical), ABCC9 (33% identical), ABCC10 (32% identical), ABCC8 (32% identical), ABCC4 (30% identical), ABCC5 (30% identical), ABCC11 (28% identical), ABCC12 (27% identical), CFTR (23% identical).
Diseases named in the same sentence as ABCC3 in open-access papers:
ABCC3 is named in the same sentence as 112 diseases in open-access papers, as found by Europe PMC text mining. Sharing a sentence is not in itself a finding about the gene and the disease. The quoted sentences say what the papers report.
breast carcinoma (40 papers, 1995 to 2026). "A high expression level of the ABCC3 gene is associated with various tumors’ poor prognosis, such as gastric cancer, breast cancer, and pancreatic cancer." (PMID 34336837, 2021). "While chemotherapy increased the gene expression of ABCC3, knocking down ABCC3 increased DOX retention in breast cancer cells and the sensitivity and susceptibility to the DOX and several other cytotoxic anti-neoplastic agents (mitoxantrone and methotrexate)." (PMID 32883003, 2020). "The ABCC3 efflux pump, in the case of breast cancer cells, is associated with HER2 positive cells, which is the case of BT-747 cells, and has been associated to a decreased rate of drug retention and with chemoresistance." (PMID 32531981, 2020). "AhR knockdown downregulated the expression of ABCC3, which is a member of the ABC gene family ABCC3 overexpression is observed in breast cancer and has been implicated in acquired MDR." (PMID 24932473, 2014). "Moreover, ABCC3 overexpression in breast cancer samples and breast cancer cell lines was associated with the increased ability of drug resistance in breast cancers." (PMID 32883003, 2020). "In contrast, ABCC3 was implicated in breast cancer stem-like features." (PMID 33081264, 2020). "In human breast cancer, ABCC3 is overexpressed in cancerous tissue, particularly in patients with human epidermal growth factor receptor 2 (HER2)-positive breast cancer." (PMID 40839607, 2025). "The overall frequency of genetic alterations in breast cancer ranged from 1% in ABCG2 to 9% in ABCC3." (PMID 40641097, 2025). "To investigate the potential involvement of other ABC transporters associated with breast cancer chemoresistance, we analysed the expression of ABCC1, ABCC3, and ABCG2." (PMID 39858449, 2025). "The study showed that, like the ABCC1 gene, the ABCC3 gene was overexpressed in stage III primary breast cancer." (PMID 36674773, 2023). "They observed that the expression level of the ABCC1 and ABCC3 genes is elevated in breast cancer tissue, especially after treatment with anticancer drugs." (PMID 36674773, 2023). "A role of ABCC3 in cancer stemness is emerging, as ABCC3 knockdown reduced the expression of stemness genes and the CD44high/CD24low breast cancer stem-like subpopulation." (PMID 36585418, 2022). "In the other solid tumors, ABCC3 overexpression induced a resistant phenotype for methotrexate and doxorubicin in breast cancer cells and it played the role in acquired resistance in HER2-amplified breast cancer." (PMID 35008510, 2021). "ABCB1 and ABCC3 proteins, members of ATP binding cassette (ABC) transporter family, are associated with chemoresistance in breast cancer cells." (PMID 32947901, 2020). "ABCC3 was identified as one of the most up-regulated genes in in chemotherapy-resistant lung cancer and taxane-resistant breast cancer." (PMID 30817750, 2019). "We observed that similar to ABCC1, the transcripts levels of ABCC3 was significantly high in breast cancers compared to adjacent normal tissue." (PMID 27171227, 2016). "We observed that similar to ABCC1, the expression of ABCC3 is elevated in breast cancers, particularly following chemotherapeutic drug treatment." (PMID 27171227, 2016). "Since knockdown of ABCC3 led to a significant retention of doxorubicin, and also decreased the breast cancer stem-like cell population, we went ahead and undertook in vivo experiments with ABCC3 knockdown cells." (PMID 27171227, 2016). "Further, our study highlights a role for ABCC3 in chemotherapy induced drug resistance and in the regulation of cancer stemness in the context of breast cancer." (PMID 27171227, 2016). "While our data on ABCC1 are consistent with previous studies, we now additionally report the increased expression of ABCC3 on chemotherapy treatment in breast cancer cells." (PMID 27171227, 2016).
breast carcinoma (continued). "Our data is consistent with previous reports on overexpression of ABCC1 in breast cancers, while additionally identifying ABCC3 overexpression in high grade breast cancers." (PMID 27171227, 2016). "We further compared the effect of ABCC1 and ABCC3 knockdown on CD44high/24low marker profile that identifies breast cancer stem cells." (PMID 27171227, 2016). "Together, our data revealed that treatment with chemotherapeutic drugs enhances the expression of ABCC1 and ABCC3 in breast cancer cells both in vivo and in vitro." (PMID 27171227, 2016). "Next we investigated the effects of chemotherapeutic drug treatment on the expression of ABCC1 and ABCC3 in established breast cancer cell lines." (PMID 27171227, 2016). "In this study we show that ABCC1 and ABCC3 were significantly overexpressed in a large number of breast cancer samples compared to normal." (PMID 27171227, 2016). "Taken together our results demonstrated that similar to ABCC1, overexpression of ABCC3 also reduces the retention of anti-cancer drugs in breast cancer cells." (PMID 27171227, 2016). "In this study, we have examined the expression of ABCC3 in breast cancers and studied its role in drug resistance and stemness of breast cancer cells in comparison with the more studied ABCC1." (PMID 27171227, 2016). "Further, similar to knockdown of ABCC1, knockdown of ABCC3 also significantly increased the retention of chemotherapeutic drugs in breast cancer cells and rendered them more chemo-sensitive." (PMID 27171227, 2016). "Consistent with this we observed that the expressions of ABCC1 and ABCC3 in chemotherapy-treated breast cancer derived tissue samples were significantly upregulated compared to chemo-naive breast cancer derived tissue samples." (PMID 27171227, 2016). "In this study we investigated the expression of ABCC1 and ABCC3 in breast cancers and assessed their role in cancer drug resistance and stemness." (PMID 27171227, 2016). "Additionally, we identified a significant association of genes involved in treatment response in breast cancer with genes producing splicing-derived neoepitopes (ERBB2, ESR1, TIMP1, ABCC3) or potentially depleted self-epitopes (AKT1, CCNE1, RET, TFF3)." (PMID 34529669, 2021). "Additionally, our data revealed an increase in the expression of ABCC3 in chemotherapy-treated breast cancer patient samples compared to chemo-naive samples, suggesting a possible role for ABCC3 in treatment-induced drug resistance in breast cancers." (PMID 27171227, 2016). "We next proceeded to test the effects of ABCC3 inhibition on drug retention in breast cancer cells." (PMID 27171227, 2016). "Interestingly, ABCC1 and ABCC3 knockdown cells also showed reduction in the expression of stemness genes, while ABCC3 knockdown additionally led to a reduction in the CD44high/CD24low breast cancer stem-like subpopulation." (PMID 27171227, 2016). "Our data further revealed a novel observation that identifies the knockdown of ABCC3, but not ABCC1, sensitizes breast cancer cells to methotrexate, a routinely used drug to treat breast cancers, together highlighting an important role for ABCC3 in breast cancer drug resistance." (PMID 27171227, 2016). "Thus, our study revealed that similar to ABCC1, ABCC3 is also overexpressed in grade III primary breast cancers." (PMID 27171227, 2016). "Since chemotherapeutic treatment itself is known to upregulate the expression of ABC transporters, thus aiding drug resistance, we next investigated the effect of chemotherapy on the expression levels of ABCC3 using breast cancer patient-derived tissue samples." (PMID 27171227, 2016). "In addition, we found a significant increase (p = 0.0006) in the expression of ABCC3 in breast cancer tissue compared to normal." (PMID 27171227, 2016). "Thus, our study reveals that, knockdown of ABCC3 significantly increases drug retention, chemosensitivity and apoptosis in breast cancer cells." (PMID 27171227, 2016).
breast carcinoma (continued). "Thus, we show that knockdown of ABCC1 and ABCC3 leads to reduction of stemness gene expression, and, importantly, that knockdown of ABCC3 further showed reduced breast cancer stem-like cell population." (PMID 27171227, 2016). "Thus, our data revealed that similar to knockdown of ABCC1, ABCC3 knockdown also increased the drug-sensitivity of breast cancer cells." (PMID 27171227, 2016). "Hence, to begin to understand the role of these transporters in breast cancer progression, we first investigated the expression of ABCC3 in grade III invasive breast ductal carcinoma tissue samples and compared it with that of ABCC1 in the same samples." (PMID 27171227, 2016). "Taken together, these results suggest that treatment with anticancer agents in combination with inhibition/down modulation of ABCC3 may be an effective clinical strategy for treating breast cancers." (PMID 27171227, 2016). "Also, our data showed that knockdown of ABCC3, significantly increased the retention of doxorubicin in breast cancer cell lines, better than that achieved by ABCC1 knockdown." (PMID 27171227, 2016). "In addition, our data identifies increased expression of ABCC3 in grade III breast cancers in comparison to normal tissues." (PMID 27171227, 2016). "Thus this study has highlighted the importance of ABCC3 in breast cancers and further suggests that targeting this transporter might help to alleviate therapy-induced resistance." (PMID 27171227, 2016). "A study on breast cancer cell lines showed a biostatistical trend (p = 0.069) between ABCC3 expression and MRP3 protein level." (PMID 39412582, 2024). "For metformin, the highest number of its targets were associated with malignant neoplasm of the prostate (six genes) and breast carcinoma (seven genes: ABCB11; ABCC2; ABCC3; ABCC4; DHFR; DPP4; SLC22A1)." (PMID 36046822, 2022). "Recently, we reported alterations in ABCC3, CPS1, and TRIP6 gene expression in a breast cancer cell line resistant to paclitaxel." (PMID 35008510, 2021). "Ca2+ is also able to elicit the expression of the ATP-binding cassette subfamily C member 3 (ABCC3), a promoter of Twist and EMT in breast cancer cells." (PMID 31849690, 2019). "ABCB1, ABCB5, ABCB8, ABCC1, ABCC2, ABCC3, and ABCG2 were considered to confer resistance to doxorubicin on the breast cancer cells." (PMID 30202239, 2018). "Consistent with this, we observed that treatment of breast cancer cell lines with anti-cancer agents increased their mRNA levels of both ABCC1 and ABCC3." (PMID 27171227, 2016). "ABCC3 is frequently amplified and overexpressed in HER2-positive breast cancer compared to HER2-negative breast cancer patient samples." (PMID 27171227, 2016). "To do so we over expressed ABCC1 and ABCC3 genes by transient transfection of pCMV-ABCC1 and pCMV-ABCC3 constructs into MDA-MB-231 and BT-474 breast cancer cell lines." (PMID 27171227, 2016). "In MDA-MB-453 and MCF-7 human breast cancer cells, CYP1A1, CYP1B1 and ABCC3 (MRP3) were up-regulated." (PMID 25713759, 2015). "We found that ABCC3, ACPP, PPP1CA, PRKAG3, and RNASEL were involved in the tumorigenesis of FMC and exhibited interactions with proteins and chemotherapeutic drugs relevant to both human breast cancer and FMC." (PMID 40839607, 2025). "Among these, ABCC3, ACPP, PPP1CA, PRKAG3, and RNASEL exhibited interactions with several proteins, immune checkpoint markers, and chemotherapeutic drugs administered in both human breast cancer and FMC." (PMID 40839607, 2025). "Balaji and colleagues examined the expression level of the ABCC1 and ABCC3 genes in breast cancer patients (without division into molecular subtypes) and assessed their role in inducing the phenomenon of resistance to anticancer drugs." (PMID 36674773, 2023). "In our studies, we also showed an increased expression level of the ABCC3 gene in the tumor tissue of patients with TNBC compared to controls, which may indicate the gene’s role in inducing multidrug resistance in breast cancer cells." (PMID 36674773, 2023).
breast carcinoma (continued). "Additionally, EGF-stimulated EMT, which transforms breast cancer MDA-MB-468 cells into a mesenchymal-like shape, increases the expression of ATP-binding cassette subfamily C member 3 (ABCC3) after Ca2+ signaling of TRPC1." (PMID 33806911, 2021). "Further, CD44high/CD24low fraction, which has been identified as the stem-like cells in breast cancer, was also reduced upon knockdown of ABCC3, but not by ABCC1 knockdown." (PMID 27171227, 2016). "Since we observed that breast cancer samples derived from patients treated with 5-flurouracil and cyclophosphamide showed upregulation of ABCC1 and ABCC3, we further went ahead to check the expression of ABCC1 and ABCC3 upon 5-fluorouracil (3 μM) treatment in breast cancer cell lines." (PMID 27171227, 2016). "Although the expression of ABCC1 in breast cancers has been investigated by multiple studies, the expression of ABCC3 has not yet been well investigated in grade III breast cancers." (PMID 27171227, 2016). "Interestingly we observed that most of the breast cancer cell lines tested (BT-474, MCF-7, T-47D, MDA-MB-231 and HCC-1806) showed significant upregulation of ABCC1 and ABCC3 compared to immortalized cell lines (HBL-100 and MCF-10A)." (PMID 27171227, 2016). "However, a functional relevance for ABCC3 expression in drug resistance and stemness aspect in breast cancers is not well established." (PMID 27171227, 2016). "In addition, we observed that treatment of breast cancer cell lines in vitro with anti-cancer drugs routinely used in the clinic to treat breast cancers (doxorubicin, mitoxantrone and 5-flurouracil) also increased the expression of ABCC1 and ABCC3 in these cells." (PMID 27171227, 2016). "Thus, our data showed that consistent with increased doxorubicin retention, knockdown of ABCC3 also reduces the IC50 for chemotherapeutic drugs, much more than the ABCC1 knockdown, suggesting that inhibition or preventing the upregulation of ABCC3 might be efficacious for breast cancer treatment." (PMID 27171227, 2016). "The knockdown of ABCC1 and ABCC3 reduced the expression of stemness genes (e.g., Nanog and Bmi1) in TNBC cell lines, and the knockdown of ABCC3, but not ABCC1, also reduced the CD44high/CD24low breast cancer stem-like subpopulation." (PMID 33801148, 2021).
cholestasis (33 papers, 2014 to 2025). Impairment of the bile flow caused by obstruction within the liver, or outside the liver in the bile duct system. "The mouse model used in this study with CCl4 administered for 1 year underwent severe cholestasis with increased Abcc3 and Abcc4 levels, which corresponds to the findings of previous studies." (PMID 38053838, 2023). "Of note, induction of hepatic ER stress in cholestasis decreases gene expression of Cyp7a1, Fxr, Abcc3 and Abcb11 similar to the pattern observed in our study)." (PMID 35948878, 2022). "Particularly, a down-regulation of Car3 and up-regulation of Gadd45a and Nqo1 is indicative of hepatotoxicity, whereas dysregulation of Abcc3 can indicate cholestasis." (PMID 27598887, 2016). "Analysis of the transporter’s expression in CLCOs revealed that SLC51A/B and ABCC3 were down-regulated by CPZ treatment, which might contribute to CPZ induced cholestasis in cholangiocytes." (PMID 38475870, 2024).